STAT1 (signal transducer and activator of transcription 1)
Diseases named in the same sentence as STAT1 in open-access papers (continued):
Sharing a sentence is not in itself a finding about the gene and the disease.
tumor (continued). "Furthermore, STAT1 phosphorylation was found to be indispensable for IFN-γ- and IL-27-induced PD-L1 expression on tumor cells and monocytes." (PMID 37131151, 2023). "Thus, higher the expression of STAT1, STAT2, STAT3, STAT4, STAT5A, and STAT5B, the lower the tumor purity." (PMID 36968603, 2023). "In conclusion, we discovered a previously unknown pro‐tumorous mechanism in which the CYP2E1‐PPAR‐γ‐STAT‐1/NF‐κB/STAT‐3/STAT‐6 axis induced GBM cell proliferation and inhibited apoptosis to fuel tumorigenesis and tumor growth." (PMID 37283464, 2023). "CXCL10, CXCL5, MMP1, CXCL12, CXCL11, CXCL2, STAT1, IL‐6 and TLR2 were hub genes in network and may promote or inhibit the homing or of immune cells in tumours and immune cell differentiation, bring intratumoral immune heterogeneity." (PMID 36524848, 2023). "In addition, blocking STAT1 inhibits the secretion of TNF-α and IFN-γ by immune cells, leading to tumor growth and metastasis." (PMID 36865498, 2023). "Interestingly, we found that IRF1, STAT1, STAT2, and STAT3 were all significantly downregulated in Scissor+ tumor cells compared to Scissor− and background tumor cells." (PMID 37021816, 2023). "Q11 does not directly affect tumor cells but blocks the tumor‐promoting effect of microglia/macrophage (M/Mφ) in the tumor microenvironment through PPARγ‐mediated activation of the STAT‐1 and NF‐κB pathways and inhibition of the STAT‐3 and STAT‐6 pathways." (PMID 37283464, 2023). "In addition, the current study also revealed the specific molecular mechanism of butyrate in upregulating PD-L1 expression via INF-γ–STAT1–PD-L1, which in turn facilitates the immune clearance of CRC and suppresses tumor progression." (PMID 37931529, 2023). "STAT1 is not the only transcription factor responsible for the transcriptomic and epigenomic changes in tumours elicited by chronic IFN-γ exposure." (PMID 37503572, 2023). "As CIN fuels karyotypic heterogeneity during tumor cell evolution, CIN will likely promote selection of karyotypes that promote activity of pro-tumorigenic non-canonical NF-κB and STAT3 signaling and inhibit tumor-suppressive STAT1 signaling programs." (PMID 37561163, 2023). "Consequently, we deduced that high expression of STAT1, STAT2, STAT4, and STAT5A indicated low BRCA tumor purity." (PMID 36968603, 2023). "In addition to STAT3, constitutive activation of STAT1 and STAT5 was also shown in tumor cells and tumor tissues." (PMID 36911202, 2023). "Thus, depletion of the JAK-STAT signalling regulator LNK impaired tumour growth and potentiated α-PD-1 responses by relieving LNK-mediated STAT1 inhibition." (PMID 37752135, 2023). "STATs including STAT1–6 may exacerbate cell growth and cancer development (STAT3 and STAT5) and regulate the anti-tumor immune responses for tumor control (STAT1 and STAT2)." (PMID 38094755, 2023). "CXCL10, CXCL5, MMP1, CXCL12, CXCL11, CXCL2, STAT1, IL‐6 and TLR2 were hub genes, which may drive the homing of immune cells in tumours and promote immune cell differentiation." (PMID 36524848, 2023). "Hence, we proposed that higher STAT1, STAT2, and STAT4 expression suggested less tumor stemness characteristics." (PMID 36968603, 2023). "In summary, our conclusions from the present study are that RHAMM contributes to primary tumor and metastasis clonal heterogeneity by regulating tumor cell survival via STING/IFNG/STAT1 signaling in microenvironments characterized by a high potential for DNA damage." (PMID 37349798, 2023). "Additionally, mRNA expression analysis demonstrated that knockdown of DVL2 resulted in upregulation of STAT1, suggesting that DVL2 acts as a negative regulator of tumor suppression." (PMID 36809986, 2023). "When we additionally verified the activation of STAT1 by the acidic tumor microenvironment, the expression of pY-STAT1 was not increased in acidic conditions." (PMID 35927628, 2022).
tumor (continued). "An anti-proliferative role of OSM was reported in immune-deficient mice injected with human melanoma cells and in a chondrosarcoma model, where local intra-tumor overexpression of OSM reduced tumor development and enhanced tumor cell apoptosis through the JAK3/STAT1 axis." (PMID 36077744, 2022). "Furthermore, in this study, we aimed at dissecting the activation of STAT1 and STAT3 in tumor cells and the immune cell infiltrate in human HCC tissue samples." (PMID 35267462, 2022). "In addition, a seven-metagene cluster (STAT1, interferon, HCK, MHC-I, MHC-II, IgG, and LCK) has been reported in several studies to illustrate the inflammatory activities in the tumor microenvironment." (PMID 35222371, 2022). "And in mechanism, IFN-γ-Stat1-Irf1 signaling was activated after the depletion of METTL3 and METTL14, leading to the increased secretion of IFN-γ, and finally enhanced the CD8+T cell-mediated anti-tumor response in the tumor microenvironment." (PMID 36058919, 2022). "STAT3 plays a dual role in tumor inflammation and immunity by promoting the pro-tumor inflammatory pathway of nuclear factor-κb (NF-κb) and interleukin-6 (IL-6)-GP130-Janus kinase (JAK) and by inhibiting STAT1 and NF-κb-mediated Th1 antitumor immune responses." (PMID 36686662, 2022). "Although these results mimic our observations in the orthotopic model, the difference in tumour development between Stat1+/+ and Stat1−/− mice in the 4NQO model was not as high as in the orthotopic model." (PMID 35595823, 2022). "However, STAT3 and STAT5 have been studied more thoroughly, while the role of STAT1, STAT2, STAT4, and STAT6 in tumor development has been studied less thoroughly." (PMID 35244291, 2022). "That STAT1 was uniformly higher in stromal tissue surrounding tumors than in the tumor cells themselves suggested that the regulation of STAT1 in tumor cells was independent of stromal cells." (PMID 35681772, 2022). "For example, in HPV infection individuals, PD-L1 expression is induced by EGFR and JAK2/signal transducer and activator of transcription 1 (STAT1)-dependent procedures; in particular, inhibition of JAK2 prevents re-regulation of PD-L1 in tumor cells, leading the increased immunologicity." (PMID 37305016, 2022). "In addition, protein levels of “p-p38, p-JAK2, and p-STAT1” were downregulated in miR-195-5p-overexpressed PTC cells and tumor xenografts, whereas CircRNA NRIP1 upregulation reversed these effects." (PMID 36230649, 2022). "IFN-γ can also establish tumor cells dormancy and inhibit tumor cells proliferation by IFN-γ/STAT1 pathway or non-STAT1 signaling." (PMID 35842707, 2022). "These STAT1-positive tumors also exhibited a high degree of immune cell infiltration, especially CD4-, CD8, and FOXP3-positive T cells, suggesting that an active engagement of the immune system with the tumor takes place and that these tumors are immune “hot”." (PMID 35267462, 2022). "Taken together, our in vitro and in vivo data using miR-155–KO tumor cells further confirms the antitumor role of endogenous miR-155 in regulating antitumor immune response by targeting SOCS1 and altering its downstream p-STAT1/p-STAT3 balance." (PMID 35925680, 2022). "Therefore, mutations and deletions of proteins related to this pathway on tumor cells, such as JAK1 and JAK2, STAT1, and IRF1, the IFNγ receptor chain, can lead to resistance to immune checkpoint inhibitors." (PMID 36185620, 2022). "PD-1 expression in CD4+T cells was reduced in spleens, but not tumours and draining lymph nodes of carcinogen-induced Stat1−/− mice compared to Stat1+/+ mice." (PMID 35595823, 2022). "Interestingly, despite the increase in STAT1 induced by TRIM24 knockdown, we observed that TRIM24 silencing inhibited the tumour promoting effects and enhanced the tumour inhibitory effects of STAT1 activation." (PMID 35595823, 2022).
tumor (continued). "Although STAT1 has long been considered to be a tumour suppressor by promoting HNSCC cell death, recent reports show that STAT1 activation also mediates programmed cell death ligand 1 (PD-L1) expression in HNSCC cells thereby promoting tumour immunosuppression." (PMID 35595823, 2022). "We observed a striking positive correlation between STAT1 and PDL1 in tumours of HNSCC patients, further supporting our hypothesis of PD-L1 regulation by STAT1 in HNSCC." (PMID 35595823, 2022). "There are seven proteins in the STAT family, among which STAT1 and STAT2 play an important role in anti-tumor immune response, STAT3 and STAT5 are related to tumorigenesis, especially STAT3 is closely related to cancer cell survival, immunosuppression, and persistent inflammation." (PMID 36686745, 2022). "Furthermore, WEE1 inhibition triggered upregulation of STAT1 which induced upregulation of PD-L1 and IFN-γ expression, but upon combination with anti-PD-L1 blockade induced anti-tumor immune response in a CD8+ T cell dependent-manner." (PMID 36551637, 2022). "DDRi-induced immune stimulation primarily occurs via the cGAS/STING pathway, but also occurs through signal transducer and activator of transcription 1 (STAT1) pathway activation and direct activation of immune cells including T cells, NK cells, and anti-tumor macrophages." (PMID 36276148, 2022). "We found that IL-6 induced STAT1 transcriptional activity upon STAT3 depletion, suggesting that HCC tumor cells may activate both STAT1 and STAT3 signaling under pro-inflammatory conditions." (PMID 35267462, 2022). "In concurrence with NanoString analysis of our own tumor samples, these included IFN-γ signaling genes STAT1, CXCL10, and IDO1; antigen presentation molecules HLA-DQA1 and HLA-DRB1; important T cell molecules GZMB and IL7R; and B cell–related molecules CD79A and CXCL13." (PMID 35132960, 2022). "However, we also observed a corresponding decrease in PD-L1 in the tumour microenvironment, which corresponds to the role of IFN-γ and STAT1 signalling in the production of PD-L1." (PMID 35595823, 2022). "Moreover, STAT1 and STAT2, which were defined as ccRCC tumor activated TFs, were also significantly upregulated in GP1 (p < 0.05)." (PMID 35440542, 2022). "Also, an adequate balance between STAT1 and STAT3 is very crucial for shaping the fate of macrophage polarization and tumor progression." (PMID 34689394, 2022). "Further, absent IFN-γ signal transduction mediated by STAT1 leads to failure to prepare immune cells for sufficient anti-tumour immune activity, as evidenced by decreased IFN-γ expression in the tumour microenvironment." (PMID 35595823, 2022). "Treatment of an immunocompetent colorectal tumor mouse model with these Man-LF NPs led to a decrease of the tumor volume concomitantly with a downregulation of the M2- related markers and TGFβ expression of TAM while the expression of STAT1 and TNF was increased." (PMID 35163420, 2022). "However, questions remain regarding the role of STAT1 expression by oral epithelial and cancer cells during stages of HNSCC tumour development." (PMID 35595823, 2022). "Further studies reveal that CRC-derived miR-21-5p and miR-200a synergistically induces macrophage M2 like polarization and PD-L1 expression by regulating the PTEN/AKT and SCOS1/STAT1 pathways, resulting in decreased CD8+ T cell activity and increased tumor growth." (PMID 35356153, 2022). "Inhibiting STAT1, EGCG may also exert anti-tumor activity e.g., by a decrease of IFN-γ-induced expression of indoleamine 2,3-dioxygenase, which enhances progression of tumor cells." (PMID 36613784, 2022). "In tumor cells, PI3K-AKT is involved in the IFN-γ induced phosphorylation of STAT1 (Ser-727)." (PMID 36195887, 2022). "We therefore surmised that SPATA2 and CYLD suppress the production of T-cell chemokines from tumor cells, in part by regulating STAT1 protein levels and restraining STAT1 signaling (but not NF-κB signaling) emanating from IFN-γ stimulation." (PMID 36531014, 2022).
tumor (continued). "Orthotopic injection of 4T1.2 cells into the mammary fat pads of BALB/c mice demonstrates that lack of STAT1 in non-tumor cells results in significantly larger primary tumors and greater numbers of lung metastases." (PMID 35681772, 2022). "A previous study suggested that STAT1 and STAT3 have opposing roles in the tumor process." (PMID 35719940, 2022). "The dual nature of STAT1 as a tumor suppressor and tumor promoter has been addressed in many studies, but no clear mechanistic details have been provided to elucidate the duality." (PMID 35406434, 2022). "Similarly, tumor tissue samples with high positivity for tumor cell nuclear STAT3 exhibited high cytoplasmic STAT3 levels and tumors with positivity for nuclear STAT1 showed increased nuclear STAT3." (PMID 35267462, 2022). "It is possible that effective short-term RT regimens promote transient production of IFN-α/β by DCs and of IFN-γ by T cells, which temporarily engage STAT1 and/or other STAT molecules in both host cells (including immune cells) and tumor cells to trigger protective anti-tumor responses." (PMID 34830176, 2021). "For example, we could identify the STAT1 expression and the MHC class I expression on each tumor cell and/or non-tumor cell in reference of the synchronous expression of DAPI and CK or not." (PMID 34758826, 2021). "IL-18 may confer protection against colitis-associated inflammation and neoplasia by modulating the permeability of the intestinal epithelium, the production of antimicrobial peptides, and the activation levels of the tumor suppressors IFN-γ and STAT1." (PMID 34639191, 2021). "Moreover, the expression of PD-L1, JAK2 phosphorylation and STAT1 phosphorylation (included S727 and Y701) were increased in MC38 tumor tissues from C57BL/6 mice after Foretinib treatment." (PMID 34307367, 2021). "These hub biomolecules of tumor stroma network, AR, GATA2, miR-124, TOR1AIP1, ESR1, EGFR, STAT1, miR-192, GATA3, COL1A1, may give crucial information about tumorigenesis." (PMID 33907495, 2021). "The role of STAT1 in tumorigenesis is complex, as its functions are not restricted to tumor cells, but extend to different compartments of the tumor microenvironment (e.g., immune cells, endothelial cells)." (PMID 34572789, 2021). "Moreover, the levels of PD-L1 in the CT26 tumor tissues were determined by western blotting after Foretinib treatment, which demonstrated that PD-L1, p-JAK2 and p-STAT1 (included S727 and Y701) were significantly increased, which was similar to the MC38 tumor." (PMID 34307367, 2021). "As the exact role of STAT1 as a tumor suppressor or oncogene is not clarified yet, more investigations are mandatory to identify STAT1 as a therapeutic target." (PMID 34638338, 2021). "From these results, we can say that tumor escape from the immune system is further facilitated by inflammatory cytokines, which are abundant in the TME of inflammation-prone tumors such as HCC, and it can be countered by using STAT1 inhibitors." (PMID 34445462, 2021). "In STAT1 knockdown tumor xenografts, radiation predominantly suppresses the glycolysis/gluconeogenesis pathway without significant change in STAT1 wildtype tumor xenografts." (PMID 34900673, 2021). "In tumor cells, PRMT5 regulates the expression of STAT1 and PD-L1." (PMID 34522232, 2021). "Besides, the protein levels of p-p38, p-JAK2 and p-STAT1 were remarkably down-regulated in miR-195-5p overexpressed PTC cells and tumor xenografts, whereas CircRNA NRIP1 up-regulation overturned the impacts." (PMID 34689819, 2021). "In addition, IL-6 is a potent activator of signal transducers and activators of the transcription (STAT) factors STAT1 and STAT3, which play an important role in the progression of neoplasia." (PMID 33922946, 2021). "Moreover, we detected the expression of LpCat1, STAT1, CyclinD1, ki67 and MMP-9 in the tumor tissues by immunohistochemistry." (PMID 34178664, 2021).
tumor (continued). "STAT1 is a member of STAT family and it serves as a double-edged sword in tumor progression." (PMID 34873163, 2021). "In addition to detecting gene expression, we found that GINS2 knockdown increased STAT1 and STAT2 protein expression and inhibited tumor migration and proliferation, which was consistent with a previous study." (PMID 33391406, 2021). "In the tumor microenvironment, IFNγ is secreted by T lymphocytes to reactivate macrophages and CD8+ T cells, but it also stimulates PD-L1 overexpression in tumor cells through the JAKs-STAT1 signaling pathway." (PMID 34685495, 2021). "Interferon-gamma produced by activated T cells binds to its receptor on tumor cells and determines STAT1 activation and transcription of IRF1/7 which in turn binds to the CD274 promoter, increases PD-L1 transcription and, ultimately, the expression on tumor cells." (PMID 33114576, 2020). "In this regard, we demonstrate herein that SPHK1 expression is increased in breast CSCs compared with non-CSCs and is involved in regulating the survival of breast CSCs and non-CSCs through repression of the tumor suppressor function of STAT1." (PMID 32260399, 2020). "On the other hand, STAT1 can inhibit angiogenesis by inhibiting hypoxia inducible factor alpha (HIF-1α) and vascular endothelial growth factor (VEGF-A), thereby promoting a decrease in tumor growth." (PMID 33076315, 2020). "A score of 0–4 was attributed to STAT1 and IDO1 levels in tumor and stroma compartments." (PMID 32444775, 2020). "Stat1 was not required for tumour elimination by CD8+ cells but for the induction of p16Ink4a by IFN-γ-producing immune cells and for an efficient cancer immune control." (PMID 32165639, 2020). "In contrast, STAT1 was not detectable in tumor cells of Stat1∆IECApcMin tumors demonstrating efficient conditional deletion." (PMID 32444775, 2020). "Elucidating the role played by STAT1 and STAT3 in the regulation of PD-L1 in HNSCC may shed light on potential therapeutic targets or factors influencing the ability of these tumours to respond to a PD-L1 blockade." (PMID 31853007, 2020). "However, a strong correlation was observed between protein expression of STAT1 and IDO1 in tumor cells and stroma cells." (PMID 32444775, 2020). "Stat1-negative tumour cells were p16Ink4a-negative and expressed Ki67 but neither pHP1γ, H3K9me3, nor SA-β-gal." (PMID 32165639, 2020). "In conclusion, we demonstrated that SPHK1 is required for breast CSCs’ and non-CSCs’ survival through suppression of the tumor suppressor function of STAT1." (PMID 32260399, 2020). "In addition, activation of STAT1 and STAT3 has an opposite effect on tumor survival and growth by regulating a plethora of effector proteins." (PMID 31957537, 2020). "Interestingly, EOC cells enriched from ascites showed constitutive phosphorylation of STAT1 and STAT3 and expression of IL-18BP and IDO1, suggestive of an in vivo role of STAT-activating cytokines in the EOC tumor environment." (PMID 32093058, 2020). "STAT1 or IDO1 protein in tumor or stroma cells did not correlate with overall survival and metastasis-free survival of patients." (PMID 32444775, 2020). "To verify the observed effects of STAT1 silencing in vivo, we compared the growth of tumors formed by HeLA/vector, HeLa/Fra-1, and HeLa/Fra-1/siSTAT1 cells in BALB/c-nu mice Tumor formation was significantly diminished in the HeLa/Fra-1 group compared with that in the HeLa/vector control group." (PMID 33102485, 2020). "Immunohistochemistry for CNOT7 and STAT1 protein expression in 49 paired HCCBC and cirrhotic hepatic tissues revealed that these proteins were expressed predominantly in the cytoplasm in tumor and cirrhotic hepatic tissues." (PMID 32160402, 2020). "While treatment with ICB/AT did not induce a senescent phenotype and did not attenuate the tumour growth in the RT2.Stat1−/− mice, the inflammatory infiltrate was similar to that of cancers in RT2.Stat+/+ mice." (PMID 32165639, 2020).